IL4 (interleukin 4)
Diseases named in the same sentence as IL4 in open-access papers (continued):
Sharing a sentence is not in itself a finding about the gene and the disease.
infection (continued). "When the infection of IL-4-stimulated cells was compared to non-stimulated cells, a significant increase in the infection rate at 24 and 48 hours after infection, as well as at the parasite load at 48h and 96h was observed." (PMID 31856207, 2019). "The significant increase in IL4 and IL5 from single to dual infection could explain the significant decrease in parasite body length in the later group of hosts." (PMID 31871660, 2019). "Consistent with our previous findings, the frequency of IL-4+ CD4+ T cells was significantly increased at all time points in the spleen (part A) and mesenteric nodes (part B), with the frequency increasing as the infection progressed." (PMID 30653492, 2019). "In view of these results it is possible to elucidate that, most probably, IL4 does not play a pivotal role in promoting the host peripheral immune response during infection with T. gondii." (PMID 31533826, 2019). "Our data revealed that 14 weeks post-infection, HisAK70-vaccinated mice showed key biomarkers of protection, such as higher iNOS/arginase activity, IFN-γ/IL-10, IFN-γ/IL-4, and GM-CSF/IL-10 ratios, in addition to an IgG2a-type response when compared to the control group." (PMID 31739549, 2019). "We found that IL-4/IL-13 enhanced in vivo infection of pmacs upon rVSV/EBOV GP challenge, but not rVSV/G." (PMID 31825972, 2019). "In particular, neutralizing antibodies, induced by ZIKV vaccines, may block infection, while CD4+ and CD8+ T cells secrete IFN-γ, IL2 (Th1), IL-4, and IL-5 (Th2) cytokines to further promote antibody production or directly kill infected cells." (PMID 31717890, 2019). "Il4 is an anti-inflammatory cytokine that increases the expression of non-canonical Wnt proteins during infection or inflammation." (PMID 30709343, 2019). "The Th2 CD4+ T cells expressing IL-4 and Treg cells expressing CD4+CD25+Foxp3+ and CD4+CD25–Foxp3+ were significantly induced at the early intestinal stage (6 days post-infection, day 6) and NBL migration stage (day 15) compared to the those of uninfected mice." (PMID 31703440, 2019). "The phagocytic uptake of Mtb at 4 h post-infection was not affected by the knockdown of either miR-143 or miR-365 in M(IL-4/IL-13) stimulated BMDMs, excluding possible antagomiR-induced cytotoxicity or inconstant uptake due to antagomiR treatment." (PMID 30941122, 2019). "Both IL-4 and IL-13 inhibit IFN-γ-producing CD4+ T-cells and suppress protective Th1 immune response and trigger MΦs to undergo alternative activation resulting in parasite survival and persistence of infection." (PMID 31024534, 2019). "In contrast, infection with rVSV/G, expressing native VSV G glycoprotein, was not enhanced by IL-4/IL-13 stimulation, suggesting that the increase in infection is specific to EBOV glycoprotein-expressing virus." (PMID 31825972, 2019). "Secretion of IL-4 of T lymphocytes from the WT-INF group (CD4: 8.01 ± 1.23%; CD8: 2.1 ± 0.23%) was also higher than TLR7-INF (CD4: 1.43 ± 0.48%; CD8: 0.94 ± 0.14%, P < 0.05) after infection." (PMID 31930147, 2019). "Immunization and/or infection did not alter cytokines IL-2, IL-4, IL-10, IL-17, IFN-γ, and TNF-α levels; however, IL-6 significantly (p < 0.05) increased, as compared with untreated control." (PMID 31065302, 2019). "To corroborate our flow cytometry data on the relative abundance of TH1, TH2 and TH17 cells using another independent methodology, we estimated the relative abundance of IL-4, IFN-γ and IL-17A transcripts in RNA extracted from splenocytes at 6 and 8 weeks post infection." (PMID 30653492, 2019). "We demonstrate in these studies that IL-4/IL-13 polarization increases the expression of cell surface receptors important for EBOV infection on mouse pmacs and human MDMs, resulting in enhanced Ebola GP-dependent infection in both wild-type and Ifnar-/- cells." (PMID 31825972, 2019).
infection (continued). "A significant number of studies from our laboratories have identified protective roles for IL-4, IL-13 and IL-4Rα signaling, not merely during primary infection with L. donovani infection, but also for effective sodium stibogluconate chemotherapy." (PMID 31475014, 2019). "Consequently, we calculated the Th1/Th2 ratio based on the relative expression levels of GATA3, IL-4, T-bet, and IFN-γ at days 10 and 28 after infection." (PMID 29535708, 2018). "At day 6 post-infection the increase in Il5 and Il13 mRNA expression in total lung was significantly reduced following anti-Ym1 treatment whilst Il4 was not significantly altered." (PMID 30500858, 2018). "Results showed that the percentages of IL-4-, IL-5-, and IL-17-producing cells in TLR3+ NK cells population significantly increased after infection (IL-4: 14.73 ± 1.968% versus 8.787.97581%; IL-5: 0.03333 ± 0.03333% versus 0.9833 ± 0.1922%; IL-17: 24.50 ± 2.466% versus 51.76 ± 2.258%, P < 0.05)." (PMID 30246036, 2018). "Prior to infection with Mtb, macrophages transfected with the siRNA targeting DC-SIGN still continue to express this CLR (albeit at minimal levels) upon activation with IL-4, ranging between 5 and 25% compared to control cells." (PMID 29946317, 2018). "IL-4 and factors released from NEC such as alarmins enhance macrophages infection by JEV." (PMID 30282716, 2018). "Consistent with our previous findings, IL-4 production was not enhanced by IL-12/ms treatment during primary infection, and IL-17 production was enhanced in all (re)infected mice regardless of IL-12/ms treatment." (PMID 29404418, 2018). "Infection increased IL-4 secretion in the PeLF by 9.8-fold in non-diabetic (CN315) and 8.6-fold in diabetic (DN315) animals." (PMID 30705678, 2018). "As such, il4−/− mice were more resistant than WT littermates during the first infection with C. albicans (probably due to the absence of a TH2 skewing) but failed to survive a secondary infection." (PMID 30555491, 2018). "A 2.2-fold increase in the amount of Igf-I mRNA was observed upon amastigote infection, a 1.2-fold increase was observed following stimulation with IFN-γ, and an 8.7-fold increase was observed when cells were simultaneously stimulated with IL-4 and IL-13." (PMID 30150896, 2018). "Basophils have been proposed as a critical early source of interleukin (IL) 4 (IL-4) following infection with helminths that polarizes CD4+ T cells to a T helper 2 (Th2) phenotype, which become a major source of IL-4 to promote mastocytosis and goblet cell hyperplasia." (PMID 30177522, 2018). "C3H mice that were treated with IL-4 or anti-IL-12 early in the infection developed a strong but transient increase in IL-4 level, with no change in their resistant phenotype." (PMID 30150896, 2018). "Interestingly, only three cytokines increased in levels throughout duration of infection: IL-2, IL-4, and TNFα, the latter being important for DENV-3 C0360/94 infection of AG129 mice." (PMID 29559699, 2018). "The early stage of infection in immunocompetent animals was marked by a mixed Th1/Th2 immune response, as characterized by the concomitant presence of gamma interferon (IFN-γ) and interleukin-4 (IL-4) and their related chemokines." (PMID 30037796, 2018). "As IL-4 depletion has been shown to enhance host resistance against tuberculosis infection, the increase of both IL-4 and VIL-4 in THP-1 cells after H37Rv infection may play roles in helping M. tb evade the host surveillance system in phagocytes." (PMID 29433383, 2018). "In this study, we show that infection with helminths (Schistosoma mansoni, Nippostongylus brasiliensis, and Heligmosomoides polygyrus) or immunization with S. mansoni Ags, expands bystander TVM cells in secondary lymphoid tissues via IL-4." (PMID 30375396, 2018). "Nevertheless, as no detectable IL-4-producing cells were observed in the skin of infected KN2 mice the possibility of IL-4 driving Th1 differentiation following infection with L. major is rather unlikely." (PMID 29067025, 2017).
infection (continued). "Following infection with L. major (LV39), IL-4−/− or IL-4Rα−/− mice on a BALB/c genetic background were able to control lesion size and the levels of IFNγ present in draining lymph node (dLN) cells was either very low or remained unchanged compared to that observed in BALB/c wild-type mice." (PMID 29067025, 2017). "Infection did not change the frequency of cells transcribing il-4 and no IL-4 production was observed 12 and 24 h after L. major infection." (PMID 29067025, 2017). "While the expression levels of IL-2 and IL-4 in calcitriol treated mice were a slightly higher following infection than in untreated mice at days 4 to 6 post-infection, there were no marked differences between the three groups." (PMID 28114957, 2017). "Overall, the serum anti-gC isotype values supported the earlier onset and overall increased antibody responses to EHV-1 challenge infection in weanlings that were vaccinated with gC/IL-4 after birth compared to non-vaccinated group 3 foals." (PMID 28045974, 2017). "Numbers of IL-4-producing cells did not change in perigonadal fat during infection whereas in the lung the number of IL-4-producing NK cells was reduced." (PMID 29040326, 2017). "Accordingly, IL-4Rα-deficient BMDCs, with reduced IL-12 and increased IL-10 secretion, failed to vaccinate BALB/c animals against acute leishmaniasis, while IL-4-sufficient BMDCs producing increased IL-12 and reduced IL-10 successfully immunized BALB/c mice against infection." (PMID 29176972, 2017). "Other enhanced immune proteins included IL-4 and IL-12 (p70) which are actively involved in T cell differentiation, activation or maturation while IP-10, MCP-1, and RANTES are chemoattractants that recruit T cells, among others, to sites of infection." (PMID 29273069, 2017). "major, no detectable levels of il4 mRNA or IL-4 proteins were locally measured during the first days of infection." (PMID 29067025, 2017). "Similarly, regulation of pro-inflammatory cytokines is controlled by the release of IL-10, therefore ups and downs inTh1 inflammatory responses, due to IL-4, and TGF-β initially up and later down-regulates during infection." (PMID 28319123, 2017). "Infection did not affect the percentages of CD4+ T cells positive for interleukin-4 (IL-4) or the activation marker CD69; however, it increased percentages of IL-17A+ CD4+ T cells by 4.0-fold." (PMID 28442605, 2017). "Taken together, the present data rule out a major role for skin IL-4 and keratinocyte IL-4Rα signaling in the development of a Th1 protective immune response following experimental infection with L. major." (PMID 29067025, 2017). "We have further studied the expression of intracellular pro-IL-1β, IFN-γ, IL-4, IL-17, and TGF-β cytokines by CD4+ and CD8+ T cells in the lungs of infected WT, Nlrp3−/−, Casp1/11−/−, and ASC−/− mice at 48 h, 2, 4, and 10 weeks of infection." (PMID 28740491, 2017). "Next, IL-4 DCs, LPS-treated DCs or IFN-α DCs were exposed to C91-PL for 3 h, purified using positive selection with anti-BDCA-4 antibodies and cultured for three days to allow productive infection." (PMID 28426803, 2017). "Serum IFN-γ and IL-4 levels, as well as intestinal sIgA levels, were measured during and 1 week after infection with Staphylococcus aureus with and without Lactobacillus plantarum treatment." (PMID 28819629, 2017). "Using in vitro monocyte-derived IL-4 DCs, TGF-β DCs and IFN-α DCs that mimic DCs contacting HTLV-1 in vivo, we show here that despite their increased ability to capture HTLV-1 virions, IFN-α DCs restrict HTLV-1 productive infection." (PMID 28426803, 2017). "Concerning TNF-α/IL-4 balance, low FEC with elevated serum antibodies and IL-4 could prove the presence of infection." (PMID 28717322, 2017).
infection (continued). "When patients were stratified by infection status, we observed increases in TNF-α, CRP, TGF-β, IL-4, IL-6, IL-10, IL-17, and IL-23, and a decrease in IFN-γ in both uninfected and infected patients when compared with control subjects at most of the three time points." (PMID 27682880, 2017). "IL-4-producing CD8+ T-cells were detected only during the La infection at 4 weeks PI, but it was present in both infections at 8 weeks PI; moreover, it was higher in the La than in the Lb infection." (PMID 27073297, 2016). "Additionally, mRNA levels of Gal-9, Tim-3, CD44, CD137, and PDI were significantly increased in the lungs at day 5 after infection, and the levels of CD137, IFN-α, IFN-β, IFN-γ, IL-4, and IL-10 in the lungs were also increased after α-lactose treatment." (PMID 27554340, 2016). "After 60 h of infection, at the more acute phase, the bacteria had induced a substantial increase in the expression of genes for most proinflammatory cytokines, including IFN-γ, IL-1β, IL-2, IL-6, IL-8, IL-22, and TNF-α, as well as genes for IL-10 and IL-4." (PMID 27357336, 2016). "Likewise, in the context of Trichinella spiralis and Leishmania major infection, treatment of wild-type mice with anti-ICOS or anti-ICOSL Abs served to diminish the Th2 immune response, reducing the production of IL-4, IL-5, and IgE." (PMID 27559335, 2016). "The immunization protocol did not induce IL-4 up-regulation post immunization, however, its level increased post challenge with infection." (PMID 27023750, 2016). "Following infection, we stimulated cells with GM-CSF in the absence of IL-4, that is, under our conditions for MAC differentiation." (PMID 26758199, 2016). "Infection of DCs with wt EBOV resulted in a significant reduction of the majority of cytokines and chemokines analyzed in comparison to mock-infected DCs, with a few exceptions, including IL-4, IL-5 and IL-13." (PMID 27930745, 2016). "Regarding IL-4 responses, there were no changes in levels detected for any infected group (G1–G3) in comparison to basal levels (prior to infection and control animals) (data not shown)." (PMID 26739099, 2016). "A few cytokines were shown to have no distinguished trend or increases following infection: GM-CSF, IL-2, IL-12, and IL-4." (PMID 27043611, 2016). "In the chronic infection at day 98 post-infection, despite the reduction in parasite load, we could not detect any modulation of IFN-gamma, IL-4, TGF-beta and IL-10." (PMID 27716449, 2016). "Multiple cytokines in RDPs, including TNF-α, IL-8, IP-10, MCP-1, MIP-1α, IL-1ra, IL-10, G-CSF, IFN-γ, IL-4 and IL-17, reached peak value in 4 to 5 weeks after infection, whereas only IP-10 and IL-13 in SPDs did so, and lack of TNF-α in SDPs." (PMID 27830756, 2016). "This confirm previous results showing increased production of IL-4 by lymph node cells of LaE-injected mice and the absence of infection-enhancing effect of this extract in IL-4-knockout mice." (PMID 25971623, 2015). "In CIITA-transgenic mice, which have a substantial population of IL-4-induced innate CD8+ T cells, this population facilitated rapid control of viremia and induction of functional anti-viral T-cell responses during infection with chronic form of lymphocytic choriomeningitis virus." (PMID 26452143, 2015). "Similarly, as early as 2 wk after infection, the splenocytes from the MGL1−/− and MGL1+/+ mice produced comparable levels of IL-4." (PMID 25664320, 2015). "Cells from mice exposed to either a low or high dose of cercariae also secreted large quantities of IFN-γ and IL-4, showing that the infection dose is not a factor in the induction of lymphocyte hyporesponsiveness." (PMID 25624353, 2015). "Thus, as the infection progressed, splenocytes from MGL1−/− mice produced significantly greater levels of IL-4 compared with splenocytes from T. crassiceps-infected MGL1+/+ mice in response to anti-CD3." (PMID 25664320, 2015).
infection (continued). "Thus coimmunization of sFliC and STm alters the IFN‐γ response to STm and the IL‐4 response to sFliC in both transgenic and endogenous CD4 T cells without altering the capacity of mice to control the early stages infection." (PMID 26036767, 2015). "On the other hand, the expression of il2 and il4 was below the detection limit in all tissues at any time point irrespective of infection." (PMID 26146835, 2015). "In the present study, we found that the IL-4/IFN-γ mRNA ratios in the spleen of vaccinated mice, or animals treated with rEmP29 saponin formulations, were lower than in spleens of mice treated with saline (infection controls)." (PMID 26053794, 2015). "On the other hand, despite the decrease in detection of IFN-γ and IL-4 in the group of mice receiving a single dose of atorvastatin along with infection, death rates were not enhanced in this group." (PMID 26732740, 2015). "Finally, pigs surviving the infection with E75CV1 showed a very consistent signature characterized by the up-regulation of IL-23, IFN-γ and NFκB and the down-regulation of IL-1β and IL-4." (PMID 26589145, 2015). "To confirm these previous observations, we measured circulating levels of IL-6 and IL-4 in a small cohort of IgAN patients and controls, all without clinical signs of infection for at least 4 weeks before sampling." (PMID 24398680, 2014). "PBS57 administration no longer affected the course of infection in these mice, supporting an important role of IL-4 in αGalCer analog PBS57-mediated disease exacerbation." (PMID 24967701, 2014). "Relative to patients with silent infections, patients with severe infections had significantly higher levels of IL-17+CD4+ cells, decreased levels of IL-17+CD8+ cells, and higher levels of IFN-γ, IL-4, IL-10, and IFN-α2 (p < 0.001 for all comparisons)." (PMID 24646014, 2014). "However, in resistant mice, the cytokine profile switches to a type-2 response (IL4, IL10) during the late/chronic stages of infection, presumably restricting prolonged and exaggerated inflammatory responses." (PMID 25375156, 2014). "The level of IL-4 production was low and similar in group of mice inoculated with wild-type L. major or inoculated with lmtkcd+/+ at week 16 post infection (data not shown)." (PMID 24873970, 2014). "For the inflammatory response, nicotine could suppress the secretion of IL-1α, IL-4, IL-5, IL-10 and RANTES on day 6 and IL-17 on day 14 significantly after H9N2 infection compared with control mice." (PMID 24465940, 2014). "Additionally, the mice pre-immunized with SGS and subsequently infected with L. braziliensis plus SGS had lower levels of IFNγ to IL-4 ratios compared to mice inoculated with PBS and infected with L. braziliensis plus SGS at 2 weeks post infection." (PMID 24421912, 2014). "The contribution of the surrounding liver tissue, however, was quite significant for other ones, e.g. IL-12, IFN-γ, IL-4 and IL-17A, at the early stage of infection; CXCL9, IL-4, IL-5, CCL17, at the middle stage; and IL-10 and TGF-β at the late stage of infection." (PMID 24637903, 2014). "These contradictory observations with IL-4 might be possibly explained by the fact that a low infection dose with L. major induces a Th2 response in C57BL/6 mice, whereas high doses induce a Th1 response, both dependent on IL-4 production by lymphocytes." (PMID 25368612, 2014). "From the results presented here, it is not possible to conclude if infection is responsible for the IL-1β, IL-6, or IL-4 cytokine production, or if other environmental or genetic differences are responsible for individual differences in cytokine levels." (PMID 24548288, 2014). "It was also observed that, in primary infections with L. amazonensis, the levels of IL-4 were not as elevated as in infections with L. guyanensis or L. naiffi when compared with the control group." (PMID 25295285, 2014).